RBM39 (RNA binding motif protein 39)
Diseases named in the same sentence as RBM39 in open-access papers (continued):
Sharing a sentence is not in itself a finding about the gene and the disease.
neuroblastoma (continued). "For example, the EED gene that encodes a critical component of polycomb-repressive complex 2 that plays a critical step in neuroblastoma growth showed exon 8 and 9 skipping after RBM39 depletion." (PMID 34788094, 2021). "We observed that one of these splicing factors, in particular, RBM39, is essential to RNA splicing in neuroblastoma cells." (PMID 34788094, 2021). "The dependence of neuroblastoma on RBM39 provides a rationale to target the altered splicing machinery in neuroblastoma using an RBM39 degrader as a therapeutic approach." (PMID 34788094, 2021). "Although RBM39 is essential to most cancer cell lines, neuroblastoma was the lineage most significantly sensitive to RBM39 RNAi compared to all other lineages (P = 0.0023)." (PMID 34788094, 2021). "On the basis of these results, we concluded that indisulam-mediated degradation of RBM39 is the mechanism of action that accounts for its antitumor effect in neuroblastoma both in culture and in vivo." (PMID 34788094, 2021). "On the basis of above results, we concluded that indisulam-mediated degradation of RBM39 is a viable strategy to target pre-mRNA splicing in MYC-driven neuroblastoma." (PMID 34788094, 2021). "RBM39 depletion led to significantly reduced neuroblastoma cell colony formation in vitro and tumor growth in vivo." (PMID 34788094, 2021). "As a key splicing regulator essential for neuroblastoma survival, RBM39 may be functionally connected to CRC TFs and epigenetic modifiers, given the tight coupling between splicing and gene transcription." (PMID 40962798, 2025). "Using neuroblastoma as an example, this study provides evidence that heterogeneous tumor cells can be eliminated by harnessing the power of the immune system through targeting the RNA splicing factor, RBM39." (PMID 40962798, 2025). "Likewise, neuroblastoma was reported to overexpress the splicing factor RBM39 and to be highly sensitive to Indisulam, a drug that promotes RBM39 degradation." (PMID 37599362, 2023). "It has been demonstrated that RBM39 is essential for RNA splicing in neuroblastoma cells." (PMID 35989423, 2022). "Collectively, these data were consistent with the hypothesis that selective degradation of RBM39 and defects in pre-mRNA splicing are likely to be the primary mechanism for the anti-proliferative effect of indisulam in neuroblastoma." (PMID 35296644, 2022). "Intriguingly, sensitivity to indisulam in neuroblastoma lines is greater than might be predicted by direct siRNA targeting of RBM39." (PMID 35296644, 2022). "Collectively, these data indicate that neuroblastoma has an inordinate dependency on RBM39-mediated RNA splicing, which may represent a vulnerability in MYC-driven high-risk neuroblastoma." (PMID 34788094, 2021). "Indisulam, a “molecular glue” that selectively recruits RBM39 to the CRL4-DCAF15 E3 ubiquitin ligase for proteasomal degradation, is highly efficacious against neuroblastoma, leading to significant responses in multiple high-risk disease models, without overt toxicity." (PMID 34788094, 2021). "S2), supporting the hypothesis that neuroblastoma is relatively more dependent on splicing factors related to RBM39." (PMID 34788094, 2021). "We therefore hypothesized that mouse neuroblastomas driven by MYC will have a dependency on RBM39 analogous to human neuroblastoma." (PMID 34788094, 2021). "The high levels of DCAF15 and RBM39 dependence in neuroblastoma might make indisulam especially efficacious against this MYC-driven cancer." (PMID 34788094, 2021). "We and others have recently reported that indisulam, a ‘molecular glue’ that selectively degrades the splicing factor RBM39, is exceptionally effective at causing tumor regression in multiple high-risk neuroblastoma models without overt toxicity, suggesting indisulam has translational potential." (PMID 38488852, 2024).
neuroblastoma (continued). "Thus, it was confirmed that DCAF15 is necessary for the mechanism of action of two RBM39-degraders indisulam and E7820 in neuroblastoma including downstream consequences such as RNA mis-splicing and perturbations to key factors in cell cycle progression and metabolism." (PMID 35296644, 2022). "To address the unmet clinical need for high-risk neuroblastoma therapy, we recently identified a therapeutic target, RBM39, a MYC target that regulates pre-mRNA splicing and appears to be essential to neuroblastoma survival." (PMID 40962798, 2025). "This suggests that RBM39, CRC TFs, and epigenetic regulators act in concert to govern neuroblastoma cell fate." (PMID 40962798, 2025). "Here, we show that neuroblastoma, a MYC-driven cancer characterized by splicing dysregulation and spliceosomal dependency, requires the splicing factor RBM39 for survival." (PMID 34788094, 2021). "We and others have shown that targeting the splicing factor RBM39 by indisulam, a ‘molecular glue’ that bridges RBM39 to E3 ubiquitin ligase DCAF15 for proteasomal degradation, achieved significant anti-tumor activity in neuroblastoma models." (PMID 38488852, 2024). "The data showed that JMJD6 co-dependency genes were significantly and positively correlated with spliceosome/mRNA splicing (i.e. RBM39, SF3B1), ubiquitin-mediated proteolysis and endocytosis and a number of 17q25 genes, which mirrored the pathway network of 17q essential genes in neuroblastoma." (PMID 38488852, 2024). "Our study indicates that targeting RBM39 in combination with anti-GD2 therapy may eradicate neuroblastoma cells irrespective of their cell state switching potential, providing a rationale to combine indisulam and anti-GD2 mAb as a therapy for high-risk neuroblastoma patients." (PMID 40962798, 2025).
leukemia (6 papers, 2019 to 2025). A malignant (clonal) hematologic disorder, involving hematopoietic stem cells and characterized by the presence of primitive or atypical myeloid or lymphoid cells in the bone marrow and the blood. "In conclusion, these findings confirm that RBM39 deletion markedly impedes leukemia progression in vivo, highlighting its potential as a therapeutic target in T-ALL management." (PMID 39044280, 2024). "Previous studies have demonstrated that RNA-binding proteins (RBPs) were frequently mutated in leukemia patients and essential for leukemia growth and differentiation, such as RBM17 and RBM39 in AML." (PMID 38216972, 2024). "have reported that degradation of RBM39 sustains leukemia survival by altering the splicing of HOXA in AML cells." (PMID 34295818, 2021).
colorectal cancer (5 papers, 2021 to 2025). A primary or metastatic malignant neoplasm that affects the colon or rectum. "RBM39 is highly expressed in most cancers and inhibition of its function causes lethal damage in a variety of cancers including lung, breast, and colorectal cancers." (PMID 38593113, 2024). "Importantly, high protein levels of MORC2, RBM39 and Slug are strongly associated with metastasis and poor clinical outcomes of colorectal cancer patients." (PMID 39048555, 2024). "In conclusion, RBM39 emerges as a promising candidate for clinical diagnosis and targeted treatment of colorectal cancer, with implications for future research in tumor biology and therapeutic strategies." (PMID 40302803, 2025). "Mechanistically, we demonstrated that RBM39 influences the malignant biological behavior of colorectal cancer through the NF-κB signaling pathway." (PMID 40302803, 2025). "In the in vivo nude mouse xenograft model, our study demonstrates that the targeted knockdown of RBM39 markedly suppresses tumor formation, highlighting a novel therapeutic strategy for combating colorectal cancer." (PMID 40302803, 2025). "Mechanistically, RNA-seq analysis indicated that RBM39 activates the NF-κB pathway, which plays a pivotal role in driving the malignant biological behaviors of colorectal cancer." (PMID 40302803, 2025). "This study elucidates a novel mechanism by which RBM39 regulates apoptosis in colorectal cancer cells, augmenting existing theories regarding its oncogenic role." (PMID 40302803, 2025). "Here, our results indicate that CDK5RAP2 S regulated by MORC2 and RBM39 promotes colorectal cancer progression." (PMID 39048555, 2024). "In summary, our results reveal a novel mechanism by which MORC2 promotes colorectal cancer development by promoting the isoform switch of CDK5RAP2 L to CDK5RAP2 S through interacting with RBM39." (PMID 39048555, 2024). "We ranked splicing factors that bind to MORC2 and selected RBM39, an RNA-binding protein that promoted the survival of colorectal cancer cells by regulating the splicing of various genes." (PMID 39048555, 2024). "We found both RNA and protein expression levels of MORC2 and RBM39 were significantly higher in colorectal cancer tissues in our cohort." (PMID 39048555, 2024). "Our findings not only provide a novel mechanism but also suggest a treatment strategy of targeting the MORC2/RBM39/CDK5RAP2 axis for colorectal cancer therapy." (PMID 39048555, 2024). "The expression level of RBM39 in normal colorectal tissues was moderate, and it showed moderate to high expression in colorectal cancer patients." (PMID 39023715, 2024). "Another study showed that the upregulated expression of RBM39 significantly increased the survival rate of colorectal cancer cells, suggesting that RBM39 has an extremely important potential function in apoptosis." (PMID 34389703, 2021). "RBM39 was identified as a potential therapeutic target for colorectal cancer." (PMID 40302803, 2025). "Next, we analyzed the expression of MORC2 and RBM39 in patients with colorectal cancer." (PMID 39048555, 2024). "The expression of RBM39 was significantly different in different stages of colorectal cancer." (PMID 39023715, 2024). "Taken together, our findings uncover a novel mechanism by which MORC2 promotes colorectal cancer metastasis, through RBM39-mediated pre-CDK5RAP2 alternative splicing and highlight the MORC2/RBM39/CDK5RAP2 axis as a potential therapeutic target for colorectal cancer." (PMID 39048555, 2024). "Additionally, RBM39 has also been reported in colorectal cancer and esophageal cancer." (PMID 34389703, 2021). "Correlation analysis revealed that MORC2 and RBM39, MORC2 and Slug, RBM39 and Slug expression were positively correlated in colorectal cancer with metastasis." (PMID 39048555, 2024).
colorectal cancer (continued). "In colorectal cancer, MORC2 binds to RBM39 to promote alternative splicing of pre-CDK5RAP2, converting CDK5RAP2 L into a variant CDK5RAP2 S. CDK5RAP2 S promotes invasion and metastasis of colon cancer cells in vitro and in vivo." (PMID 39048555, 2024). "The results demonstrated that MORC2, RBM39, and Slug were highly expressed in colorectal cancer tissues with metastasis, while E-cadherin was not or lowly expressed." (PMID 39048555, 2024).
gastric cancer (5 papers, 2023 to 2025). A primary or metastatic malignant neoplasm involving the stomach. "Taken together, this work and previous data revealed that both USP39 and RBM39 promoted the growth of gastric cancer cells and their high expression was associated with poor patient survival." (PMID 39260689, 2024). "A recent study has shown that RBM39 regulated cell proliferation by affecting the splicing of MRPL33 in gastric cancer cells." (PMID 40223119, 2025). "We also elucidated the molecular mechanism by which USP39 promotes the growth and metastasis of gastric cancer cells partially by regulating RBM39." (PMID 39260689, 2024). "Our work also demonstrated that USP39 accelerated the growth and metastasis of gastric cancer cells partially through RBM39." (PMID 39260689, 2024). "To further confirm the potential correlation between USP39 and RBM39, we immunoblotted these two proteins in different gastric cancer cell lines and in paratumor and tumor tissues from gastric cancer patients." (PMID 39260689, 2024). "Next, we sought to ask how USP39 elevates the RBM39 protein level in gastric cancer cells through the following experiments." (PMID 39260689, 2024). "We further investigate the influence of USP39 on the growth and metastasis of gastric cancer cells and reveal the molecular mechanism by which USP39 executes its biological function and its association with RBM39 expression." (PMID 39260689, 2024). "It has been reported previously that RBM39 mediates the indisulam-induced cytotoxicity in several types of cancer cells and the indisulam-inhibited proliferation of gastric cancer cells." (PMID 36805336, 2023). "Although it has been shown that USP39 has played significant roles in regulating the ubiquitination and stability of multiple proteins, it is unclear whether it impacts RBM39 and regulates its biological functions in gastric cancer cells." (PMID 39260689, 2024). "After we demonstrated the interaction between USP39 and RBM39, we sought to test whether and how USP39 regulates RBM39 in gastric cancer cells." (PMID 39260689, 2024). "Our previous work discovered that RBM39 promoted the growth of gastric cancer cells and this work revealed that USP39 upregulated RBM39." (PMID 39260689, 2024). "Therefore, we asked whether USP39 modulates these functions in gastric cancer cells through RBM39." (PMID 39260689, 2024). "Expression of USP39 significantly elevated RBM39 while USP39 knockdown attenuated RBM39, which was also observed in HGC27 gastric cancer cells." (PMID 39260689, 2024). "However, it is unknown how RBM39 is regulated in gastric cancer cells." (PMID 39260689, 2024). "However, how RBM39 is regulated in gastric cancer cells is unknown." (PMID 39260689, 2024). "It should be noted that other DUBs (such as USP50, USP51, USP52, JOSD3, and UAF1), which were identified to potentially regulate RBM39 in the biochemical screening, neither have high mRNA expression in gastric cancer tissues nor affect the overall patient survival based on the database analysis." (PMID 39260689, 2024). "Interestingly, overexpression of RBM39 partially restores the impact of USP39 depletion, while RBM39 knockdown partially abolishes the effect of USP39 overexpression on the growth, colony formation, migration, and invasion of gastric cancer cells." (PMID 39260689, 2024). "Third, to test whether this interaction occurs endogenously in gastric cancer cells, we immunoprecipitated endogenous USP39 from MKN45 and HGC27 cell lysates using an anti-USP39 antibody and protein A/G agarose and detected the presence of endogenous RBM39 in the immunoprecipitates." (PMID 39260689, 2024). "Since our previous work revealed that RBM39 mediated the indisulam-inhibited proliferation and this work demonstrated the role of ZEB1 in the regulation of indisulam-inhibited migration of gastric cancer cells, we did not explore the function of RBM39 on indisulam-regulated migration." (PMID 36805336, 2023).
viral infection (4 papers, 2016 to 2025). "After the virus infection, we observed that both RBM39 and c-Jun proteins had nuclear-cytoplasmic trafficking and co-localization (down)." (PMID 34079549, 2021). "Knockdown of RBM39 or treatment with indisulam, an aryl sulfonamide drug targeting RBM39 for proteasomal degradation, strongly reduced the induction of interferon-stimulated genes (ISGs) in response to double-stranded RNA (dsRNA) or viral infections." (PMID 40330464, 2025). "Therefore, the mechanism of the precursor RNA splicing function of RBM39 and other RNA binding proteins after virus infection is worth exploring." (PMID 34079549, 2021). "SiRNA knockdown and indisulam treatment were used to study the role of RNA-binding motif protein 39 (RBM39) in innate immunity upon poly(I:C) or cytokine treatment and viral infections." (PMID 40330464, 2025).
cholangiocarcinoma (2 papers, 2022 to 2024). A carcinoma that arises from the intrahepatic biliary tree (intrahepatic cholangiocarcinoma) or from the junction, or adjacent to the junction, of the right and left hepatic ducts (hilar cholangiocarcinoma). "Increasing evidence indicates that RBM39 influences the growth of a range of malignancies, including cholangiocarcinoma, rectum adenocarcinoma, kidney clear cell carcinoma, kidney papillary cell carcinoma, lung SCC, and HNSCCs." (PMID 39201614, 2024).
glioblastoma (2 papers, 2021 to 2025). The most malignant astrocytic tumor (WHO grade IV). "While the precise mechanisms remain to be fully elucidated, these findings provide a strong rationale for co-targeting RBM39 and MGMT to overcome temozolomide resistance in cancers with high MGMT expression, including glioblastoma and neuroendocrine neoplasms." (PMID 41300971, 2025).
lung carcinoma (2 papers, 2021 to 2025). "This network revealed alternative SEs associated with RBM39, suggesting its potential regulatory role in splicing mechanisms in lung cancer." (PMID 40465651, 2025). "Intriguingly, we detected a statistically significant elevation of RBM39 expression in human lung cancer (compared with carcinoma versus para-carcinoma) using an immunohistochemistry assay." (PMID 40465651, 2025). "Through database analysis, we found that RBM39 is significantly expressed in lung cancer at both RNA and protein levels." (PMID 40465651, 2025). "RBM39 plays an important role in the occurrence and development of lung cancer." (PMID 34389703, 2021). "This study shows that RBM39 is methylated by PRMT6, which determines the resistance to Indisulam in lung cancer models due to aberrant splicing events." (PMID 40465651, 2025). "In order to further explore the role of RBM39 in the growth and migration of NSCLC cells, studies have shown that RBM39 was mainly located in the nucleus of lung cancer cells." (PMID 34389703, 2021).
acne (1 paper, 2025). An inflammatory process of the sebaceous glands which is characterized by comedones, nodules, papules and/or pustules on the skin. "Clinical cohorts with diverse acne severities and C. acnes phylotypes could enhance translational relevance, while CRISPR–based gene editing of HNRNPA2B1 or RBM39 in skin models could clarify their causal roles in inflammation and comedogenesis." (PMID 41614864, 2025). "Central to our findings are the hub genes HNRNPA2B1, HNRNPM, and RBM39, identified through the protein–protein interaction (PPI) network analysis as key regulators of acne pathogenesis." (PMID 41614864, 2025).
asthma (1 paper, 2025). "The results identified MEblack as a cluster containing 741 asthma-related core genes, including POMP, GUSBL2, RBM39, PSMA6, RFX1, TCEB1, PSMD6, and others." (PMID 41403444, 2025).
colon adenocarcinoma (1 paper, 2024). "GEPIA database analysis showed high MORC2 and RBM39 mRNA expression in colon adenocarcinoma tissues." (PMID 39048555, 2024).
colon cancer (1 paper, 2024). "Taken together, these data indicate the direct interaction between MORC2 and RBM39 in the nucleus of colon cancer cells." (PMID 39048555, 2024). "Indisulam-mediated RBM39 degradation causes splicing defects in a broad range of genes, including TRIM27, and inhibits proliferation of colon cancer cells." (PMID 39048555, 2024). "Then we verified that MORC2 and RBM39 promoted EMT in colon cancer cells." (PMID 39048555, 2024). "Importantly, MORC2 was positively correlated with RBM39 expression in colon cancer." (PMID 39048555, 2024). "In this study, our data demonstrate the functional links between MORC2, RBM39 and the downstream CDK5RAP2 whose alternative splicing they regulate in EMT and metastasis of colon cancer cells." (PMID 39048555, 2024). "Taken together, MORC2 and RBM39 promote EMT, migration and invasion of colon cancer cells via CDK5RAP2 S." (PMID 39048555, 2024). "Here, we identified a novel target gene CDK5RAP2, whose alternative splicing was regulated by RBM39 and MORC2, contributing to a better understanding of the mechanisms of RBM39 and MORC2 in colon cancer." (PMID 39048555, 2024). "However, whether MORC2 regulates RBM39-mediated alternative splicing in colon cancer is not known." (PMID 39048555, 2024).